IL6 (interleukin 6)
Diseases named in the same sentence as IL6 in open-access papers (continued):
Sharing a sentence is not in itself a finding about the gene and the disease.
autism (continued). "In our previous study, we found that the levels of TNF-α and interleukin-6 were significantly increased in children with autism." (PMID 35002603, 2021). "The upregulation of JAK-STAT signaling has also been noted in autistic children, but there is insufficient evidence at present to establish reliable causal links between aberrant IL-6, JAK1 dysfunctions and autism from this data." (PMID 35046931, 2021). "Postmortem studies have demonstrated the presence of brain neuroinflammation in patients with autism, as shown by marked activation of astrocytes and microglia together with abnormal chemokine and cytokine levels, such as IL-6, IL-8, IFN-γ, TNF-α, and TGF-β1." (PMID 34193257, 2021). "In comparison to controls displaying developmental disabilities other than autism, plasma levels of cytokines IL-1β, IL-6, IL-8 and IL-12p40 were increased in children with ASD, which correlated with the severity of the disease." (PMID 34589798, 2021). "It was also found that metabolites like tryptophan and cytokine IL6 showed the highest levels in the autism group with abdominal pain." (PMID 32532137, 2020). "In the cerebellum of children with autism, a significant increase in IL-6 expression has been demonstrated." (PMID 31071949, 2019). "The myeloid dendritic cells, which produce among others TNF- α and IL-6, have been associated with increased GI symptoms in ASD as well as increased amygdalar volume and regressive autism." (PMID 31835709, 2019). "Five already reported autism associated pro-inflammatory cytokines [interferon-γ (IFN-γ), interleukin-1β (IL-1β), IL-6, IL-12, and tumor necrosis factor-α (TNF-α)] were detected in plasma by enzyme-linked immunosorbent assay (ELISA) analysis." (PMID 30941018, 2019). "We also found elevated plasma IL-6 levels in our rat model, which has been considered to be one of the key mechanistic pathways in autism." (PMID 29791472, 2018). "Future studies focusing on the central nervous system (e.g., neuroinflammatory pathways and the production of IL-6 by astrocytes) would be interesting to improve the understanding of the possible mechanisms involved with autism." (PMID 29791472, 2018). "Both doses of pioglitazone (0.25 and 1.0 mg/kg/day, between PND 21 and 29) ameliorated the social interaction and vocalization deficits and the increase in the IL-6 levels induced in our rat model of autism." (PMID 29791472, 2018). "IL-6 and serotonin levels were increased in autistic patients compared to controls and had a positive correlation with autism severity." (PMID 28870209, 2017). "In a mouse model with elevated IL-6 in the brain, Wei and colleagues have shown that IL-6 can modulate autism-like behaviors through impairments of synapse formation, dendritic spine development, and neuronal circuit balance." (PMID 28238116, 2017). "Previous reports on autism include findings regarding changes in IL-1β, IL-10, IL-6, IL-17, and IL-12 cytokines and differential cellular immune response associated with disease severity and impairment in behaviors in ASD." (PMID 27983615, 2016). "Significant differences were found to IL-1β, IL-6, IL-17, IL-12p40, and IL-12p70 cytokines in individuals with autism compared with AMTD (p < 0.05)." (PMID 27983615, 2016). "Another study reported that IL-6 was significantly increased in the cerebellum of 6 children with autism compared to 6 age-matched control children." (PMID 24795645, 2014). "A new study CHARGE (Childhood Autism Risks from Genetics and Environment)has found a significant increase in a number of cytokines in plasma includingIL-1β, IL-6, IL-8, and IL-12 p40 in an ASD group compared with typicallydeveloping controls." (PMID 21573053, 2011). "Elevated IL‐6 levels are characteristic of individuals with autism." (PMID 39401991, 2025).
autism (continued). "These extreme elevations exceed those required to produce neurodevelopmental effects in experimental maternal immune activation models, where maternal IL-6 injection creating plasma concentrations of 100–500 pg/mL reliably produces autism-relevant phenotypes in offspring." (PMID 40843696, 2025). "Food refusal, characteristics of autism, limited variety, and tactile sensitivity served as dependent variables in relation to IL-1β, IL-6, age, and gender." (PMID 40002751, 2025). "A study on children with ASD in China supports these findings, identifying IL-6 as a factor influencing autism risk and symptom severity, although significantly elevated levels did not impact autism risk and symptom severity." (PMID 40002751, 2025). "The interleukin-6 convergence zone between 6.0 and 8.0 picograms per milliliter represents the range where Long COVID and autism profiles show the greatest similarity, encompassing approximately 30% of autism cases and 60% of Long COVID patients." (PMID 40843696, 2025). "A recent study indicated that induced pluripotent stem cells (iPSC)-derived astrocytes from patients with autism also exhibited overexpression of immune relevant genes, such as TGFB1, TGFB2, and IL6 that was associated with DNA hypomethylation of TGFB2, IL6, and TNFA gene promoter regions." (PMID 40643545, 2025). "Similarly, serum concentrations of IL-6 were elevated in boys with autism compared to controls, with higher values observed in the younger age subgroup." (PMID 39337983, 2024). "Helminth supports anti-inflammatory Th2 immune response, reverting pro-inflammatory Th1 activation, sustaining gastrointestinal homeostasis, and also increasing production of IL-3, IL-4, IL-5, and IL-10 which can lower IL-6, IL-1B, and IL-12, increased in autism." (PMID 38398873, 2024). "Notably, higher levels of IL6 were also reported in the brain, blood cells, and plasma of patients with autism." (PMID 38994948, 2024). "We also observed higher expression of IL6 in NSCs, astrocytes, and neurons in patients with autism." (PMID 38994948, 2024). "Future studies comparing a group of children and adolescents without neuropsychiatric disorders but with low MD adherence would help to clarify whether the increase in salivary IL-6 concentration is due to low MD adherence, autism, or both." (PMID 39189164, 2024). "However, after differentiation, IFI16 exhibited significant up-regulation in the astrocytes, whereas IL6 was upregulated in both astrocytes and neurons of patients with autism." (PMID 38994948, 2024). "Examination of cytokines and chemokines in archived maternal serum samples in the Early Markers for Autism (EMA) study demonstrated that elevated levels of GM-CSF, interferon-γ, IL-1α, and IL-6 were associated with autism spectrum disorder with intellectual disability." (PMID 37950045, 2023). "They demonstrated that the proinflammatory cytokines IL-12, IL-6, IL-1β and INFγ were significantly increased in patients with severe forms of autism, while the increase in the anti-inflammatory IL-10 was a protective factor against autism." (PMID 36835652, 2023). "Indeed, overexpression of TNF-α, IL-6, and IL-17 genes observed in the brain of patients with autism seriously impaired the dendritic spine development and promoted autistic-like features." (PMID 35334937, 2022). "Similarly, the proinflammatory IL-6 cytokine derived from the placenta also has an impact on social behavior in autism." (PMID 35328471, 2022). "The elevation of IL-6 in the brain could involve in the mediation of autism-like behaviors through impairments of neuroanatomical structures and neuronal plasticity." (PMID 33240114, 2020). "They revealed an increase in the plasma levels of TNF-α, IL-8, and IL-6 might be partially responsible for developing autism." (PMID 33269154, 2020).
autism (continued). "MIA inflammatory mouse models have been developed, which demonstrate autism-like behavior and were found to have elevation of the pro-inflammatory signal interleukin-6 (IL-6) with resultant fetal neuronal death, inhibition of neurogenesis, and impaired neuronal migration." (PMID 30629642, 2019). "Moreover, it is well known that multiple neuro-inflammatory mediators, which are involved in the etiology of autism, are usually released in response to IL-1 α; these mediators include IL-6, TNF- α, prostaglandins, and cyclooxygenase-2." (PMID 31733650, 2019). "Activation of astrocytes and the subsequent pro-inflammatory cytokines release, including interleukin 6 (IL-6), tumor necrosis factor alpha (TNFα), and interleukin 1B (IL-1B), has also been observed in autism within the brain as well as peripherally in the cerebrospinal fluid." (PMID 29234492, 2017). "Interestingly, in a rodent maternal immune activation (MIA) model for autism, a single injection of IL-6 to pregnant mice at gestational age of 12.5 days was reported to result in deficits in certain behaviors in the adult offspring." (PMID 25344730, 2014). "Although elevation of IL-6 is a repeated finding in autism, the exact mechanism by which an IL-6 increase may contribute to the pathogenesis of this disorder remains undefined." (PMID 25407263, 2014). "Lower ADA activity in patients with autism might also be related to the increased levels of interleukin-6 and tumor necrosis factor-α, and the impaired Ca2+ and K+ homeostasis that were reported from two studies using the same investigated autistic samples." (PMID 22958401, 2012). "By contrast, elevated concentrations of IL-2, IL-4 and IL-6 were significantly associated with an increased risk of DD without autism." (PMID 21810230, 2011). "Children with attention deficit hyperactivity disorder demonstrate interleukin-6 levels ranging from 3.1 to 6.2 picograms per milliliter with tumor necrosis factor-alpha between 6 and 15 picograms per milliliter, representing intermediate elevation compared to autism profiles." (PMID 40843696, 2025). "Therefore, investigating whether neutralizing IL-6 with antibodies can alleviate autism-like behaviors in the STAg-MIA mouse model presents an important question." (PMID 41150800, 2025). "Indeed, inhibiting IL-6 trans-signaling improves social behavior in a mouse model of autism." (PMID 34887755, 2021). "Similarly, a previous study suggested that autism-like behavior may be induced by overexpression of pro-inflammatory cytokines, such as IL-6, which regulate the organization of neural cells in the brain." (PMID 29447237, 2018). "Background/Objectives: Elevated cytokine levels, including IL-6 and IL-1β, can contribute to persistent brain inflammation in children with autism and cytomegalovirus (CMV) infection, exacerbating autism-related behaviours and symptoms." (PMID 40002751, 2025). "Thus, IL-6 may contribute to autism pathogenesis through neuroinflammatory mechanisms." (PMID 40002751, 2025). "Inflammation at age 9 years mediated effects of neurodivergent traits on chronic disabling fatigue (indirect effect via IL-6: ADHD b=1.08 (95% CI=1.01 to 1.15); autism b=1.06; (95% CI=1.03 to 1.10))." (PMID 39038862, 2024). "The activation of astrocytes and microglia in the cortex and cerebellum leads to the increased expression of IL-6, TNF-α, and MCP-1 in different brain regions of individuals with autism." (PMID 39065682, 2024). "In contrast to BDNF and IL6, we observed decreased expression of IFI16, an anti-inflammatory gene, in the NSCs of patients with autism." (PMID 38994948, 2024). "Further research with larger cohorts is warranted to conclusively determine the implications of CXCL8, IL-6, and TNF-alpha in early childhood autism." (PMID 39337983, 2024). "Compellingly, proinflammatory cytokines, including tumor necrosis factor-alpha (TNF-α), interleukin-6 (IL-6), IFN-γ, have exhibited significant upregulation in the brains of individuals with autism." (PMID 37815997, 2023).
autism (continued). "Previous studies have shown that high levels of IL-6, TNF-α, and IL-1β are correlated with the severity of autism symptoms, which include stereotypical behaviors and impaired communication skills." (PMID 36268027, 2022). "Altogether, we suggest that monocytes are the predominant cells contributing to the elevated cytokine levels of IL-6, TNF-α, and IL-1β in autism, along with CD4+ T cells, which act as another source of IL-1β, whereas neutrophils are another source of IL-6." (PMID 36268027, 2022). "Collectively, we found increased levels of IL-6, IL-17, TNF-α, IL-1β, IFN-γ, RANTES, and IL-8 in the plasma/serum in autism, which is overall consistent with the findings from previous systematic reviews." (PMID 36268027, 2022). "In this review, we found elevated levels of IL-6, TNF-α, and IL-1β in the plasma/serum of individuals with autism." (PMID 36268027, 2022). "The main targets of JWYHT on social communication disorders in autism, including MAPK, AKT1, 5HT1B, and IL6, were investigated using network pharmacology and molecular docking technology in this study." (PMID 35178102, 2022). "In this review, we found that IL-6, IL-17, TNF-α, and IL-1β were increased in the in the serum but unchanged in the plasma in subjects with autism." (PMID 36268027, 2022). "Of these biomarkers, autism has a link to tumor necrosis factor-alpha (TNF-α), interleukin 8 (IL-8), interleukin 6 (IL-6)." (PMID 33269154, 2020). "In another study, the same authors found increased levels of IL-6 and TNF-α, and decreased diurnal variation of cortisol (VAR) in patients with autism compared to controls." (PMID 28870209, 2017). "Levels of glutamate, GABA, glutamate/GABA, TNF-α, IL-6, IFN-γ and IFI16 were compared between patients with autism and age-matched control subjects." (PMID 25407263, 2014). "The immune phenotype of BTBR mice draws several parallels to observation in children with autism particularly high IL-12, IL-6, and MCP-1 production observed in both children with autism and BTBR mice." (PMID 24062633, 2013). "Thus, increased IL-6 expression may be partially responsible for the pathogenesis of autism." (PMID 21595886, 2011). "However, our findings imply that the increased IL-6 in autistic brain may not be responsible for the possible apoptotic changes associated with autism." (PMID 21595886, 2011). "Our prior publication has shown that IL-6 is elevated in the brains of MIA offspring and contributes to the neuroinflammatory state, and demonstrated that the adoptive transfer of Tregs effectively reversed most autism-like phenotypes." (PMID 41150800, 2025). "Several studies also indicate that increased levels of IL-6 and IL-1β induced by CMV infection may impact the nervous system, particularly in patients with neurological disorders such as autism or other neurodegenerative diseases." (PMID 40002751, 2025). "Several studies indicate that individuals with autism may have an immune system dysfunction in the CNS, leading to elevated cytokine levels such as TNF-α, IL1.β, and IL-6." (PMID 39720795, 2024). "Our results showed that maternal diabetes-mediated autism-like offspring had significant GI symptoms, together with suppressed RORA expression in PBMC and increased secretion of proinflammatory cytokines, including IL1β, IL6, MCP1 and IL17A." (PMID 35164690, 2022). "Furthermore, stereotypic behavior, a core symptom of autism, seemed to correlate with down-regulation of TGF-β1 and GM-CSF, as well as up-regulation of IL-1β, IL-6, IL-8, IL12p40, TNF-α, and interferon (IFN)-γ." (PMID 35328471, 2022). "The current study demonstrated that PPA-induced autism in rats was characterized by a significant increase in the expression of TNF-α, IL-6, IL-17, CCL-3, CCL-5, and CXCL-16 levels as a down-regulation of OPG in the brain of PPA-induced autism-like rats, compared to the control animals." (PMID 35334937, 2022).
autism (continued). "Elevated IL-6 levels have been described in monocytes and neutrophils at both baseline and after in vitro stimulation in autism, whereas augmented TNF-α levels have been described only in the post-stimulated monocytes of individuals with autism." (PMID 36268027, 2022). "Multiple autism rodent models of MIA have been described in the literature including mid-gestation maternal exposure to lipopolysaccharide (bacterial mimic), Poly I:C (viral mimic), or IL-6." (PMID 30629642, 2019). "Elevated serum levels of IL-6 and IL-17A, increased serum IL-6 level, and increased expression of the inflammatory molecules IL-1β, IL-6, IL-17, and TNF have been observed in children with autism." (PMID 31293459, 2019). "TLR4 has been shown to play a critical role in the maternal immune activation mouse model of autism, in which prenatal infection-induced activation of TLR4, and subsequent elevation of the key inflammatory cytokines IL6 and IL17α, are responsible for autistic-like behavior observed in pups." (PMID 29678176, 2018). "Maternal administration of the viral substitute poly (I:C) produced autism-like behavior in mice that was dependent on IL-6 and was absent in IL-6 knock-out mice." (PMID 26190965, 2015). "An alternative profile of increased IL-2, IL-4 and IL-6 was more common for women who gave birth to a child subsequently diagnosed with DD without autism." (PMID 21810230, 2011). "Thus, in addition to inflammatory activity, IL6 contributes to NSC growth, and its higher expression may induce the higher growth rate of NSCs in autism observed in our studies." (PMID 38994948, 2024). "We hypothesised a neurodevelopmental pathway from childhood neurodivergent (autism, ADHD) traits to experiencing chronic disabling fatigue in adolescence and tested whether increased peripherally circulating inflammatory markers (IL-6) impacted on this relationship." (PMID 39038862, 2024). "However, strong evidence was lacking to establish the causation between IL-6 and JAK1 abnormalities with autism." (PMID 38026692, 2023). "Interestingly, the increase in IL-6, IL-17, TNF-α, and IL-1β in the serum was in accordance with the elevated levels of these cytokines in in vitro stimulated neutrophils, monocytes, and CD4+ T cells in individuals with autism, as compared with controls." (PMID 36268027, 2022). "Notably, both IL-6 and CRP levels are elevated in the plasma in the individuals with autism." (PMID 31733650, 2019). "The expression of IL-1β, IL-6, IL-17, and TNF inflammatory molecules is increased in the brain, cerebrospinal fluid, and serum of some patients with ASD, whereas NF-kB is activated in the brain, which then stimulates peripheral blood immune cells in patients with autism." (PMID 28808521, 2017). "However, our results showed elevated IL-6 and IL-2 in mothers bearing a child with DD but not autism." (PMID 21810230, 2011). "Noteworthy, IL6 is viewed to play a crucial role in the development and plasticity of CNS and it has been described to be involved in maternal immune activation (MIA), which may contribute to the development of autism, again through the establishment of prenatal pro-inflammatory pathways." (PMID 31578139, 2019). "IL6 and TNFA promoter regions were also hypomethylated in the astrocytes of patients with autism but not in the neurons." (PMID 38994948, 2024). "Additionally, the levels of IL-6 and IL-17, but not TNF-α and IL-1β, were consistently higher in the unstimulated neutrophils, monocytes, and CD4+ T cells in autism subjects, as opposed to the controls." (PMID 36268027, 2022).